PSMB9 (proteasome 20S subunit beta 9)
Diseases named in the same sentence as PSMB9 in open-access papers (continued):
Sharing a sentence is not in itself a finding about the gene and the disease.
cancer (71 papers, 2008 to 2025). A tumor composed of atypical neoplastic, often pleomorphic cells that invade other tissues. "Based on the DEGs, we performed GSEA across all cancer types to investigate cancer hallmarks associated with PSMB9." (PMID 41020834, 2025). "PSMB9 shows widespread dysregulation, predominantly upregulated in most malignancies and linked to specific pathological stages, correlating with divergent survival outcomes across cancers." (PMID 41020834, 2025). "Thus, we set out to investigate the impact of the PSMB9 codon 60 polymorphism on the expression and activity of the β1i immunoproteasome subunit in a panel of human cancer cell lines." (PMID 24040045, 2013). "PSMB9 degrades damaged or unneeded proteins by breaking peptide bonds and may limit the presentation and processing of antigens, making the PSMB9 gene an attractive candidate for raising cancer risk." (PMID 38025532, 2023). "Targeting NLRC5 promoter demethylation through TRED-I system can upregulate MHC-I, B2M, TAP1 and genes encoding immune proteasome components (LMP2/PSMB9/β1i, LMP7/PSMB8/β5i), thereby enhancing CD8+T cell-mediated anti-cancer immunity." (PMID 40191187, 2025). "We found widespread dysregulation in PSMB9 across cancers, predominantly upregulated in most malignancies and associated with advanced pathological stages in specific contexts." (PMID 41020834, 2025). "Recent studies in various cancer types have shown that overexpression of IP subunits (PSMB8, PSMB9, PSMB10) is associated with improved survival and better response to ICI therapies." (PMID 41222746, 2025). "The PSMB2-5 and PSMB9 expression was also increased in Ki-67-positive tumors, which is consistent with increase of these genes’ expression in malignant tumors compared to normal tissue." (PMID 39796785, 2025). "Considering the role of PSMB9 as antigen-presenting machinery, the possible role of PSMB9 in shaping the immunotherapy response of cancers has garnered increasing attention recently." (PMID 41020834, 2025). "Collectively, these findings establish PSMB9 as a context-dependent biomarker whose expression delineates divergent clinical trajectories across multiple cancer lineages." (PMID 41020834, 2025). "Given the multifaceted roles of PSMB9 in cancer biology and immunotherapy, a comprehensive analysis of its prognostic value and impact on the immunotherapy response across different cancer types is therefore necessary." (PMID 41020834, 2025). "The immunoproteasome composed of the production of PSMB9 helped present antigens, triggering the recognition and destruction of cancer cells by CD8+ T cells." (PMID 39252305, 2024). "PSMB8 and PSMB9 are the most universally correlatedgenes across different cancer types, suggesting highly coordinatedproteasome activity with the HLA-I level." (PMID 37857377, 2023). "Previous studies that centered on the correlations between malignant tumors and PSMB9 mRNA expressions came to consistent conclusions." (PMID 35693739, 2022). "We explored the expression of PSMB9 in pan-cancer using TCGA and GTEx datasets, and the results show that PSMB9 was upregulated in most tumors, including LGG." (PMID 35928883, 2022). "As PSMB9 could be closely related to immune responses, interfering with cancer occurrence and progression, we then investigate the correlation between PSMB9 expression level and immune cell infiltration." (PMID 41020834, 2025). "Interestingly, six genes among these (ABCB1, FGF2, CXCR4, IL6, PSMB9, and CLU), as well as UGCG, are known to be highly associated with cancer resistance to platinum-based chemotherapy." (PMID 40507922, 2025). "PSMB8, PSMB9 and PSMB10 are part of the immunoproteasome complex, which is activated in response to interferon gamma signaling, and has been previously associated to cancer cell survival and progression." (PMID 38519482, 2024). "PSMB9 participates in a variety of biological processes and accelerates the progression of cancer." (PMID 35928883, 2022).
cancer (continued). "Our results indicated that β1i is frequently expressed in colon and pancreatic cancers, but the codon 60 PSMB9 polymorphism has no significant impact on the catalytic activity of β1i expressed in multiple types of cancer cell lines." (PMID 24040045, 2013). "Furthermore, co-amplification of PSM genes located in close proximity to one another (e.g. PSMB5 and PSMB11, 14q11.2; PSMB4 and PSMD4, 1q21.3; PSMB8 and PSMB9, 6p21.32) or known cancer drivers (e.g. co-amplification of ERBB2 and PSMB3) were also frequently amplified together." (PMID 36123629, 2022). "Additionally, other PSM genes have been associated with cancer progression (e.g. PSMD9 (p27) and PSMD10 (p28)), increased radiation sensitivity in breast cancer (e.g. absence of p27), as well as, increased risk of colorectal cancer (e.g. PSMB8 and PSMB9)." (PMID 36123629, 2022). "In the cancer, cell death, and cellular function network, 19 mRNAs and 19 proteins were differentially expressed, including MYC, PSMB9, and RPL9." (PMID 40700094, 2025). "Moreover, the addition of citrulline could restore the levels of total and phosphorylated STAT1 and PSMB9 proteins in response to IFNγ in ASS1-expressing cancer cells grown in an arginine-depleted medium, confirming the essentiality of arginine for the cancer cell response to IFNγ." (PMID 41511309, 2025). "In comparison to other cancer types, STS showed high expression of PSMB5, PSMB6 and PSMB7, the subunits of the constitutive proteasome and low levels of PSMB8, PSMB9 and PSMB10, the subunits specific to immunoproteasomes." (PMID 32851475, 2021). "Despite being essential in cellular and immunological functions, the role of PSMB8 and PSMB9 has not been determined in all types of cancers, as highlighted in at least 78 publications, including 19 meta-analyses." (PMID 36937130, 2023). "Given that the amounts of PSMB8- and PSMB9-expressing cells increase with grades, but correlate with prolonged RFS in TNBC, we next wanted to determine if amongst higher-grade cancers, the benefits of PSMB8/9 expression are even greater." (PMID 36746983, 2023). "In this study, we first demonstrated the relationship among PSMB8, PSMB9, PSMB10, PSME1, PSME2, and IRF1 in the immune micro-environment and immune score through TCGA whole cancer cohorts, and further, we proved the correlation between PSMB8, PSMB9, PSMB10, PSME1, PSME2, IRF1, and immune cells." (PMID 36700205, 2022). "Based on transcriptomic analyses of thousands of samples from The Cancer Genome Atlas, we report that expression of constitutive proteasome (CP) genes (PSMB5, PSMB6, PSMB7) and immunoproteasome (IP) genes (PSMB8, PSMB9, PSMB10) is increased in most cancer types." (PMID 27659694, 2016). "Critically, we first established PSMB9 as a novel prognostic indicator for both checkpoint blockade and CAR-T cell therapies, highlighting its dual role as a crucial immune modulator and a promising biomarker for guiding T cell-based immunotherapy strategies across diverse human cancers." (PMID 41020834, 2025). "Interestingly, for six genes (KISS1, CXCR4, PSMB9, ABCB1, FGF2, and IL6) found to be up-regulated along with GCS, their overexpression pursuant to platinum-agent treatments in patients promoted resistance to those same agents in cancers." (PMID 40507922, 2025). "However, although NMFs secreted arginine rescued cancer cells from apoptosis under arginine-deprived conditions, co-culture with NMFs alone failed to restore JAK-STAT signaling in cancer cells exposed to IFNγ, as indicated by persistently low pSTAT1 and PSMB9 protein levels." (PMID 41511309, 2025).
infection (34 papers, 2007 to 2023). The state of being infected such as from the introduction of a foreign agent such as serum, vaccine, antigenic substance or organism. "Novel EMT proteomic biomarkers (keratins 2, 6A and 20, collagen 12A1, desmoplakin) and inflammatory biomarkers (PSMB9, FGL2) were associated with early infection and barrier dysfunction." (PMID 36639424, 2023). "In response to inflammation or infection, proteolytic subunits of constitutive proteasome are replaced by immunoproteasome subunits Psmb8, Psmb9 and Psmb10 that are more efficient in processing endocytosed antigens for subsequent MHC I-restricted cross-presentation." (PMID 36993973, 2023). "These included chemokine ligand IP-10 and genes controlled by pro-inflammatory cytokines TNF-α, IL-1β, IFN-γ; namely, interferon regulatory factor 1, Cd274 antigen, metallothionein 2, proteasome subunit (Psmb9), and tumor necrosis factor Tnfsf10 were progressively up-regulated after infection." (PMID 20082697, 2010). "Among the infection-specific ISGs upregulated during ΔHA-Cre infection are genes associated with apoptosis (Ripk2, Casp1, Ifi27, Pmaip1) and E3 ubiquitin ligases and proteasome genes, some of which are known to be involved in MHC-I antigen processing (Neurl3, Rnf19b, Psmb9)." (PMID 32790753, 2020). "We then silenced each of the top four upregulated PSMBs (PSMB1, PSMB4, PSMB8 and PSMB9, fold change >1.5) using shRNA in HEK293T cells and examined the viral replication in PSMB-silenced cells after VSV-expressing GFP (VSV-GFP) infection." (PMID 30682859, 2019). "The upregulation of ISGs (i.e. CXCL9, IRGM1, PSMB9, STAT1 and UBD) in DBA/2 compared to C57BL/6 mice was confirmed by RT-qPCR at all days post-infection." (PMID 23006927, 2012). "Whether and how the simultaneous absence of the inducible catalytic subunits β1i/LMP2 (Psmb8), β2i/MECL-1 (Psmb9) and β5i/LMP7 (Psmb10) alters the course of infections remains unclarified." (PMID 33968021, 2021).
neurodegenerative disease (3 papers, 2023 to 2025). A disorder of the central nervous system characterized by gradual and progressive loss of neural tissue and neurologic function. "Besides its immune-related role in UBC, PSMB9 serves a clear role in intracellular protein degradation in neurodegenerative diseases." (PMID 36937130, 2023).
hematological malignancies (2 papers, 2017 to 2025). "This dichotomy may reflect context-specific dependencies: amplification could enhance PSMB9-mediated antigen presentation in solid tumors, whereas deletion in hematological malignancies might disable immune recognition." (PMID 41020834, 2025).
myopathy (1 paper, 2014). A disease of the muscle in which the muscle fibers do not function properly. "In all patients with inflammatory myopathies (IM) including PM, DM and OM, immunoproteasomal subunits PSMB8 and PSMB9 were significantly increased when compared to NIM patients." (PMID 25098831, 2014).
respiratory disease (1 paper, 2020). "A recent genome-wide methylation study indicated the top-associated CpG site of cg04908668 in the PSMB9 gene might implicate in nitrogen dioxide (NO2)-exposure-related lung function damage or respiratory disease." (PMID 32867763, 2020).
PSMB9 also shares sentences with these, for which no sentence is quoted: nasopharyngeal carcinoma (33 papers); gastric carcinoma (11); Hodgkins lymphoma (9); cervical carcinoma (8); prostate carcinoma (7); uterine leiomyosarcoma (7); latent infection (6); lung cancer (6); Burkitt lymphoma (5); Alzheimer disease (4); dermatomyositis (4); Stroke (4); cardiovascular disease (3); Cognitive impairment (3); Huntington disease (3); ischemia (3); leukemia (3); pancreatic cancer (3); T cell lymphomas (3); adenocarcinoma (2); adenoma (2); B-cell lymphoma (2); brain ischemia (2); cardiac hypertrophy (2); cardiomyopathy (2); Cerebral ischemia (2); colon adenocarcinoma (2); connective tissue disorder (2); emphysema (2); Epstein-Barr virus infection (2).
A further 101 diseases each share a sentence with PSMB9 in 2 papers or fewer.